IFNG (interferon gamma)
Diseases named in the same sentence as IFNG in open-access papers (continued):
Sharing a sentence is not in itself a finding about the gene and the disease.
tumor (continued). "A minor NK subset, within total circulating NK cells (5–10%), exhibits the CD56brightCD16− phenotype and is able to produce high and constant levels of anti-tumor cytokines, such as IFNγ and TNFα, CD56brightCD16− NK cells are abundant in healthy and neoplastic solid tissues." (PMID 31057536, 2019). "Upon activation, NK cells attack tumor cells through releasing cytotoxic perforin and granzyme and activating apoptosis in tumor cells through the production of IFNγ and TNF or via direct cell contact through death receptor-mediated pathways such as the TRAIL and FASL pathways." (PMID 32039025, 2019). "In addition to its effects on the CD4+/CD8+ ratio, lycopene also increases the number of IFNγ expressing CD8+ T cells in tumor tissues." (PMID 30948928, 2019). "Studies have shown that PD-L1 expression can be induced by extrinsic stimulation such as interferon-gamma produced by surrounding tumor cells, and by the activation of intrinsic oncogenic pathways, such as STAT3, an activating EGFR mutation or ALK translocation." (PMID 30961670, 2019). "The same vaccine was also able to induce a broad IFNγ-associated T-cell response in patients with advanced or recurrent HPV16-induced gynaecological carcinoma but did not induce tumour regression or prevent progressive disease." (PMID 31277636, 2019). "Furthermore, CD8 T cells produced increased levels of TNFα and IFNγ in T-PNU treated animals supporting a crucial role for CD8 T cells in T-PNU-mediated tumor rejection." (PMID 30665463, 2019). "Furthermore, the induced NO (iNOS) by NK cells when cultured with tumor cells in the presence of recombinant IL-2 that in turn induced IFNγ production that in turn enhance the cytotoxic effects of NK cells." (PMID 31457012, 2019). "Afterwards, the expression levels of 12 cytokines including IL-1a, IL-1b, IL-2, IL-4, IL-6, IL-8, IL-10, IL-12, IL-17A, TNFα, IFNγ and GM-CSF in secretome of hWJ-MSCs alone as well as in supernatant of tumor cells before and after treatment with hWJ-MSCs secretome were evaluated." (PMID 31857970, 2019). "Analysis of culture supernatants revealed that the presence of tumor cells markedly induced IFNγ production by NK cells, which constitutes an important effector mechanism by which NK cells shape adaptive immune responses and contribute to tumor immunosurveillance." (PMID 30813611, 2019). "It is known that IFNγ itself promotes expression of PD-L1 and PD-L2 in tumor cells, as well as in stromal cells, including immune infiltrating cells, thereby suppressing the effector functions of tumor-specific T cells and NK cells via PD-1." (PMID 31779626, 2019). "This is also the first study suggesting that despite its ineffectiveness as a single agent, anti-PD-1 antibody in combination with a vaccine therapy is now able to enhance the IFNγ-expressing, epitope-specific T cells in the tumor microenvironment of a “cold” tumor such as PDAC." (PMID 31113479, 2019). "This was despite the fact that in vitro, NK cells could kill YUMM1.1 tumor cells and secrete IFNγ, which up-regulated MHC-I on the tumor cells." (PMID 30718660, 2019). "IFNγ activates the transcription factor STAT1 to inhibit tumor cell proliferation and angiogenesis." (PMID 32117199, 2019). "Using Interferon-gamma (IFNγ) production as a read out of tumor-specific recognition and signaling we demonstrated that some TIL cultures were able to mount a response against a 1-2mm fragment of autologous tumor following 24h co-culture whilst other co-cultures were non-reactive." (PMID 31398192, 2019). "Moreover, increased levels of interleukin (IL)-10 were detected in tumours of treated mice, that were accompanied by decreased levels of IFNγ." (PMID 29988113, 2019). "Interestingly strong trends towards increased plasma levels of cytokines and chemokines associated with protective anti-tumor immunity was also evident including: IL-1b, IL-12, MIP1a, MIP1b, MCP-1, IL-15, IFNγ, IFNα, IL-1R, IP-10, MIG, IL-8." (PMID 31426803, 2019).
tumor (continued). "Thus, this dual function of stimulatory and regulatory effects of IFNγ on anti-tumor immunity can be exploited by vaccine-activated CD4+ T cells." (PMID 30956760, 2019). "It seems that the mechanism underlying the tumour growth inhibition in low and high dose DCG treated mice is different, as more IFNγ secreting T cells were infiltrated to the tumour site in high dose DCG treated mice, while more IL-9 secreting T cells were observed in low dose DCG treated mice." (PMID 31183361, 2019). "We found that only two out four tumour cell lines increased PD-L2 expression upon exposure to IFNγ." (PMID 30723303, 2019). "In addition, T-helper-1 (Th1) cells as well as some of the cytokines that these cells produce (e.g., interleukin-12 (IL-12) and interferon-gamma (IFN-γ)) help to maintain tumor cells in a state of immune-mediated dormancy." (PMID 31766399, 2019). "Similarly, TDEs can activate macrophage-induced tumor invasion and metastasis function by inhibiting interferon gamma (IFNγ) and IL-16 and increasing secretion of IL-8 and C-C motif ligand 2 (CCL2) in target cells." (PMID 31635338, 2019). "Since IFNγ signaling is an important mechanism for PD-L1 upregulation, we hypothesized that an impairment in downstream IFNγ signaling within tumor cells might explain this phenomenon." (PMID 31125352, 2019). "The exposure of tumor cells to certain important cytokines like IFNγ, TNFα, and IL-1 was shown to increase ROS production by tumor cells themselves in various cancer types, while the elevated ROS levels were attributed to NOX elevation or mitochondria activity." (PMID 30935064, 2019). "Moreover, the unique cat with clinical FeL confirmed by cytology was IFNγ-p and, despite possible immunosuppression due to FeLV infection and to neoplasia, this cat reached an IFN-γ level around the median value." (PMID 30909952, 2019). "NK- and T-cell-derived IFNγ levels in GBM patients’ tumours may be low due to limited NK cell infiltration into the tumour parenchyma." (PMID 31319548, 2019). "In spite of this low frequency, recognition of tumor cells treated with αCDCP1-EBV_1 ATPP could readily be detected by IFNγ ELISA." (PMID 31555260, 2019). "Moreover, the generated NK cells show a strong IFNγ expression upon cultivation with K562 tumor cells and demonstrate a high cytotoxicity toward leukemic as well as solid tumor cell lines in vitro." (PMID 31457007, 2019). "The findings from the present study confirm previous report, which showed that the DC + TL + TRF treatment approach inhibited tumor growth and metastasis by promoting Th1 immune response through stimulating production of interferon-gamma (IFN-γ) and interleukin-12 (IL-12)." (PMID 31783698, 2019). "In addition, IFNγ production by effector CD4+ T cells facilitates anti-tumor reactivity by blocking neo-vascularization, directly inhibiting tumor cell proliferation and upregulating tumor-expressed MHC molecules that improve CTL recognition." (PMID 30956760, 2019). "We analysed if the pharmacologic inhibition of MET, currently explored in the clinic as therapeutic option for MET-amplified tumours, could modulate the IFNγ-pathway and consequently PD-L1/PD-L2 regulation." (PMID 30723303, 2019). "In an IL-4-dependent manner Stat6 has been suggested to promote colorectal cancer due to its ability to polarize myeloid cells in a wound–healing/tumor-promoting alternative phenotype, which differentiates these cells from the tumor-suppressing IFNγ-mediated classical activation phenotype." (PMID 30353167, 2019). "In this model, tumor infiltrating macrophages, NK cells and T cells secreting IFNγ and TNFα and expressing TRAIL were responsible for suppression of lung metastases since neutralizing TRAIL antibodies blocked antitumor activity leading to increased lung metastases." (PMID 31333662, 2019).
tumor (continued). "To further analyse whether CAR-147 macrophage reinfusion causes cytokine storms like CAR-T cell infusion does, we detected the cytokines IL-1β, IL-6, IL-12, TNFα, and IFNγ in serum samples and tumour homogenates." (PMID 31570753, 2019). "Results that ICB could induce production of intra-tumoral IFNγ in mouse models and human patients, as well as the dependence of tumor infiltration on IFNγ receptor by immune cells, indicated a key role of IFNγ in rejecting tumor." (PMID 30948928, 2019). "TNFα and IFNγ are often expressed in the tumors' microenvironment and these signals may be altered when tumor cells are passaged in culture." (PMID 30833945, 2019). "We then evaluated if MET-inhibition interfered with IFNγ upregulation in human tumour organoids." (PMID 30723303, 2019). "Tumor-associated CD8+ T cells expressing exhaustion markers across all four tumor types project onto activated CD8+ T cells in our map, and express genes within the Cytokine module (CCL3, CCL4, XCL1, XCL2, and IFNG), and to a lesser extent Cytotoxic module." (PMID 31624246, 2019). "Interestingly, this systemic immune response is accompanied by induction of IFNγ-mediated adaptive immune resistance markers, despite significant growth control of the distant, contralateral tumor." (PMID 30323352, 2019). "These two helper T cell subtypes were co-enriched in the same patient clusters, despite being thought to be associated with different processes; that is, Th1 cells induce IFNG expression and anti-tumor effects while Th2 release IL-4 and IL-10, which help allow for tumor-escape." (PMID 30956762, 2019). "It has also been proposed that the observed upregulation of PD-L1 on tumor cells could be a direct consequence of IFNγ production by activated tumor-infiltrating T cells, which is associated with a better prognostic outcome." (PMID 30992475, 2019). "Additionally, given the link between inflammation and IFNγ-induced upregulation of PD-L1 expression in tumor, IFNγ signature has also been shown to be a biomarker of response to ICB in multiple cancer types." (PMID 31816940, 2019). "Interferon-gamma (IFN-γ) has been shown to be detected in tumor cells with PD-L1 positive and TILs, and act as a primary inducer for PD-L1 expression, while it could not be detected in PD-L1 negative tumor cells." (PMID 31139018, 2019). "The opposite tumoricidal and protumor effects of IFNγ/STAT1 signaling may be attributed to the difference of the tumor-specific context, the magnitude of the signal, and the microenvironmental cues." (PMID 31113461, 2019). "However, there were no observable increases in the expression of the proinflammatory cytokines tested (IL-2, TNF-α, and IFNγ) within the tumor tissues." (PMID 30979375, 2019). "Using four different human tumor cell lines, sCD80, but not an irrelevant Fc-linked protein, maintained IFNγ production by PD-1+ CD4+ and CD8+ T cells from human donors." (PMID 31001479, 2019). "IFNγ is usually seen as a positive mediator of the anti-tumour immune response." (PMID 30872676, 2019). "In addition to driving adaptive immune resistance, IFNγ also promotes chemokine expression which, in turn, can recruit additional immune cells into the tumor." (PMID 30873179, 2019). "Also, the activation of Tumor Necrosis Factor (TNF) family ligands that expressed on the surface of NK cells with IL-2, IL-15, IL-12, IL-18, and CD40 cytokines production induce NK cell cytotoxicity against tumor target cells and IFNγ production." (PMID 31457012, 2019). "In the cancer setting, a similar phenomenon occurs as tumor-infiltrating T cells upregulate multiple co-inhibitory receptors and are limited in their ability to produce multiple effector cytokines (such as IFNγ and TNFα), making them less polyfunctional and unable to clear the tumor." (PMID 31244852, 2019).
tumor (continued). "M1 subset of macrophages have been positively co‐related with NSCLC as they inhibit tumor growth by secretion of pro‐inflammatory cytokines like IFNγ, expression of inducible nitric oxide synthase, major histocompatibility complex (MHC) molecules, and reactive oxygen and nitrogen intermediates." (PMID 30997737, 2019). "This indicates that SV plus α4-1BB mAb induces anti-tumor IFNγ production activity." (PMID 31307539, 2019). "Similarly, mice that received anti-PD-1 showed a greater number of TNFα+ and IFNγ+ DNT cells in the tumor." (PMID 30857561, 2019). "In the current paper, we demonstrated that intravenous administration of DCG spores to TC-1 tumour bearing mice elicited strong splenic as well as tumour local immune responses, characterised by increased IFNγ or/and IL-9 secreting T cells in the spleen and the tumour site." (PMID 31183361, 2019). "TGFβ, IFNγ, and G-CSF were found to be increased in tumor-injected slices without association with microglia depletion." (PMID 31186414, 2019). "T cells and tumor stromal cells activate MDSCs through TLRs, IFNγ, IL-4, IL-13, and TGF-β." (PMID 32039025, 2019). "This suggests that Lm-ANXA2 alone may have a limited capability of inducing antigen-specific, IFNγ expressing T cell infiltration into the tumor microenvironment." (PMID 31113479, 2019). "Therefore, the tumor microenvironment seems to play a significant role in limiting the activation of NK cells that can kill tumor cells through IFNg." (PMID 30616690, 2019). "Altogether, our data demonstrate that platelet-derived RANKL impairs NK cell antitumor reactivity with a less pronounced effect on cytotoxicity compared to production of IFNγ as second major effector mechanism by which NK cells contribute to tumor immunosurveillance." (PMID 30813611, 2019). "The numbers of tumor antigen-specific T cells and IFNγ production in TdLN were determined; (iii) C57BL/6 mice that received vaccination with β-lap-induced dying MC38-OVA cells in the presence of anti-HMGB1Ab were rechallenged with MC38-OVA for evaluation of the antitumor protection." (PMID 31324798, 2019). "Indeed, the link between PD-L1 expression in both tumor and immune cells can roughly be explained by interferon gamma, which is produced by the tumor infiltrating immune cells and is one of the molecular mechanisms inducing PD-L1 expression." (PMID 31484986, 2019). "One phase II trial assessed the use of injecting Mo-DCs loaded with tumour lysate and matured by TNFα, Poly I:C, and IFNγ in 15 patients with surgically amenable liver metastasis of colon adenocarcinoma that underwent neoadjuvant chemotherapy, surgery and adjuvant chemotherapy." (PMID 31091774, 2019). "The role of IFNγ in anti-tumor immunity could be highlighted by resistance of tumors to interferons that leads to their evasion from the immune system." (PMID 30948928, 2019). "The multifunctional effects of IFNγ are particularly important in the context of immunotherapy since enhanced antigen presentation improves immune recognition of tumors while expression of immunosuppressive molecules limits anti-tumor T cell activity." (PMID 29977240, 2018). "Also, A2V can increase PD-L1 expression via interferon-gamma (IFNγ) signaling and combining PD-1 blockade and A2V can improve the anti-tumor activity in certain tumor models." (PMID 29560266, 2018). "The exclusion of HPMo induced by IFNγ may be crucial in dictating the efficacy of T lymphocyte action observed in many tumour immunotherapies." (PMID 29367702, 2018). "Specifically, targeting CAFs increases bioavailability of chemotherapeutic agents including doxorubicin and gemcitabine, while enabling immunological surveillance and tumor destruction through a process that engages interferon-gamma (IFNγ) and tumor necrosis factor alpha (TNF-α)." (PMID 28929459, 2018). "Furthermore, our study suggests that LNT treatments (1.0 mg/kg) inhibit tumor vascular function via IFNγ production and in a T cell-independent manner." (PMID 30373628, 2018).
tumor (continued). "Another important aspect for STAT1β being the more successful key marker in tumor defense than STAT1α is the fact that STAT1β acts as a dominant negative regulator in IFNγ signaling and that the best characterized signaling axis for PD-L1 is its induction mediated by IFNγ." (PMID 30647851, 2018). "Furthermore, γδ T cells secrete pro-inflammatory cytokines, such as TNFα and IFNγ, upon activation by tumor cells." (PMID 30038626, 2018). "We hypothesized that the better survival of cases with tumor-margin PD-L1 expression is explained by accumulation of activated T-cells and IFNγ release in the adjacent stroma." (PMID 29942303, 2018). "T-cell lines generated from PCa patients using the agonist peptide showed high levels of lysis of PAGE4-expressing tumor cells and enhanced secretion of Interferon gamma (IFN-g), granzyme B, Tumor Necrosis factor alpha (TNF-a), Interleukin 2 (IL-2) and lymphotactin." (PMID 29914187, 2018). "Blocking of the EGFR with cetuximab when tumor cells were stimulated with the type 1 cytokine IFNγ and TNFα resulted in the amplification of the production of the T-cell attracting chemokines and resulted in an increased migration of CD4+ and CD8+ lymphocytes in chemotaxis assays in vitro." (PMID 30192802, 2018). "Since TGFβi NK cells have remarkably increased anti-tumor IFNγ secretion, we hypothesized that TGFβ imprinting modified the transcription factors important for IFNγ secretion." (PMID 30400618, 2018). "Current findings suggest that tumor growth might be inhibited by targeting the immunosuppressive milieu through local delivery of R848, IFNγ, or TNFα." (PMID 29632539, 2018). "The regulatory capacity of IFNγ to dictate luminal retention of proangiogenic monocytes may play a pivotal role in tumour growth inhibition induced by T cells." (PMID 29367702, 2018). "However, interferon gamma (IFNg) from activated T cells can induce tumor cells to express chemoattractants CXCL9 and CXCL10." (PMID 30400835, 2018). "However, the role of IFNγ in immune modulation of tumor microenvironment by MDSCs remains unexplored." (PMID 30039553, 2018). "Thus, interferon gamma is key in protecting the host from developing tumors, but it also facilitates tumor escape mechanisms from the immune system." (PMID 29368638, 2018). "Indeed, the data show that when IL-2/IL-12-activated NK cells were switched into glutamine-deficient conditions, metabolic rates of OXPHOS and glycolysis decreased dramatically and IFNγ production and tumour cytotoxicity was substantially inhibited." (PMID 29904050, 2018). "Furthermore, LY3300054 therapy resulted in prominent immune-related gene expression changes consistent with IFNγ pathway and T cell activation in the tumor tissue, as well as in spleen and peripheral blood cells, and to a much lesser extent in the bone marrow." (PMID 29712568, 2018). "However, when the tumor cells were also stimulated with the type 1 cytokine IFNγ and TNFα an increased expression of CCL2, CCL5, CXCL9, CXCL10 and IL-6 was detected when compared to treatment with the control antibody." (PMID 30192802, 2018). "Differentiation of T cells into either of these cell types inhibits the generation of the other, yet while Tregs are known to promote immunosuppression and tumor growth, intra-tumoral Th17 T cells can increase IFNγ production and tumor infiltration by CD8 TILs, NK cells, and DCs." (PMID 29487705, 2018). "However, pulsing the tumor cells with α-GalCer and adding IL-12 at the same time synergized to allow for IFNγ production to occur." (PMID 29559971, 2018). "Consistently, CXCL10 was strongly induced by interferon gamma in normal and tumor thyrocytes." (PMID 29416784, 2018). "Thus, this review helps us to comprehensively understand the roles of IFNγ in tumor immunity, which contributes to better design and management of clinical immunotherapy approaches." (PMID 30039553, 2018). "Both IFNγ and IL-8 were significantly different between tumor bearing PDX groups." (PMID 30513792, 2018).